MCL1 (MCL1 apoptosis regulator, BCL2 family member)
Diseases named in the same sentence as MCL1 in open-access papers (continued):
Sharing a sentence is not in itself a finding about the gene and the disease.
breast carcinoma (continued). "CAFs-induced MCL-1 upregulation has also been shown to protect breast cancer cells from apoptosis during cell detachment, also known as anoïkis." (PMID 33080792, 2020). "In summary, we report here that mTOR-dependent translation of Mcl-1 increases Mcl-1 expression and promotes cell survival in ER+ breast cancer cells." (PMID 31595181, 2019). "As a first step to sort out factors involved, we therefore searched for cytokines whose mRNA expression positively correlated with that of MCL-1 expression in the luminal breast cancer expression data set used above." (PMID 30631150, 2019). "The anti-apoptotic Bcl-2 family member Mcl-1 is highly expressed in all breast cancer subtypes, although relatively little is known about Mcl-1 in breast tumor biology." (PMID 31595181, 2019). "Although classically described as inhibitors of apoptosis, cIAP-1, XIAP, Mcl-1, and survivin have been shown to modulate cell migration and metastasis in cancer models, including breast cancer." (PMID 31614718, 2019). "The results of this research indicate that ChPL induces apoptosis in breast cancer cells through MAPK-mediated Mcl-1 inhibition, suggesting further research into its potential in breast cancer treatment." (PMID 31404252, 2019). "The importance of targeting Mcl-1 in breast cancers is supported by studies carried out on Bcl-2 family proteins examining their upregulation in various types of breast cancers." (PMID 31404252, 2019). "Studies presented herein support a wider impact of mTORC1 signaling on Mcl-1 expression, highlighting the mTORC1-to-Mcl-1 axis in PIK3CA-wild type ER+ breast cancer cells (e.g. HCC1428)." (PMID 31595181, 2019). "In contrast, Bcl-xL and Mcl-1 are widely expressed in ER+ breast cancers, as well as in HER2-amplified and triple negative breast cancers (TNBC), both in pre-malignant lesions and in high grade tumors." (PMID 31595181, 2019). "At the genetic level, MCL1 is the most frequently amplified anti-apoptotic Bcl-2 family member in ER+ breast cancers." (PMID 31595181, 2019). "Anti-apoptotic MCL1 is a major resistance factor in chemotherapy, and essential in breast cancer development." (PMID 31803618, 2019). "Because this pathway has well established positive effects on MCL-1 expression and survival, we infer it exerts context dependent MCL-1 mediated survival effects in luminal breast cancers." (PMID 30631150, 2019). "The MAP kinase signaling pathway, which plays an important role in breast cancer progression, has been shown to regulate Mcl-1 expression." (PMID 31404252, 2019). "We confirmed that VU661013 blocked Mcl-1 interactions with Bim in situ in ER+ breast cancer cells using PLA." (PMID 31595181, 2019). "We report here that blockade of Bcl-2 or Bcl-xL, alone or together, rapidly induced mTOR signaling in ERα+ breast cancer cells, rapidly increasing cap-dependent Mcl-1 translation." (PMID 31595181, 2019). "Herein we show that increased Mcl-1 translation upon ABT-263 treatment drives survival of ERɑ+ breast cancer cells." (PMID 31595181, 2019). "MAP kinase activation increases Mcl-1 expression leading to cell survival, implicating the role of Mcl-1 in apoptotic cancer cell evasion and breast cancer therapeutic resistance." (PMID 31404252, 2019). "The present study aimed at determining the antiproliferative activity of 3-chloroplumbagin (ChPL), a naphthoquinone derived from a Dionaea sp., toward breast cancer cells and examining the involvement of Mcl-1 inhibition in ChPL-induced cell death." (PMID 31404252, 2019). "Studies based on ex vivo cultures of human luminal breast cancer tissues further argue that the contribution of stroma-derived signals to MCL-1 expression shapes BCL-2 dependency." (PMID 30631150, 2019). "Mcl-1 upregulation has been determined in 28% of human breast cancer cell lines as reported by the cancer cell line encyclopedia (CCLE), whereas Bcl-2 is upregulated in 3%." (PMID 31404252, 2019).
breast carcinoma (continued). "In brief, dovitinib had induced autophagy in breast cancer cells through inhibiting STAT3/Mcl-1 axis and resulted in the formation of autophagy." (PMID 31485222, 2019). "Altogether, these results show that factors secreted by CAFs led to MCL-1 induction and MCL-1 dependent resistance to the apoptotic effects of BCL-2 inhibition in the neighboring breast cancer cells." (PMID 30631150, 2019). "Although a positive correlation between PIN1 and Mcl-1 has only been reported in human breast cancer, deregulated Mcl-1 expression is also commonly found in HCC." (PMID 32010690, 2019). "The second category of agents that can have synergy with the MCL1 inhibitor in therapy resistant breast cancer are other BCL2 family (BCL2, BCL-XL, BCL-w) inhibitors." (PMID 31370269, 2019). "On the other hand, the use of a MAP kinase inhibitor U0126 protected breast cancer cells from EGF-induced Mcl-1 overexpression." (PMID 31404252, 2019). "Since the expression of MCL-1 in triple negative breast cancer is high, the ability of ChPL to decrease Mcl-1 levels in MDA-MB-468 cells points to its promising potential in breast cancer treatment." (PMID 31404252, 2019). "For example, the Ras/Raf/MEK/ERK pathway activated in breast cancer MCF-7 cells can induce binding of Noxa (a BH3-only protein) to Mcl-1 (a Bcl-2 family member) such that Beclin1 is derived from Mcl-1 on the dissociation." (PMID 31835352, 2019). "Overexpression of Mcl-1 has been seen in various human tumors, including hematologic leukemia, ovarian cancer, prostate cancer, lung cancer, breast cancer, and pancreatic cancers." (PMID 31171771, 2019). "The mechanisms of acute Mcl-1 upregulation in response to Bcl-2/Bcl-xL inhibition remain undefined in in ERα+ breast cancers." (PMID 31595181, 2019). "Mcl-1 upregulation in response to the Mcl-1 inhibitor S68345 has been reported previously in HER2-amplified breast cancers and TNBC." (PMID 31595181, 2019). "Although combined inhibition of Bcl-2 and Bcl-xL using ABT-263 is capable of inducing apoptosis in ERɑ+ breast cancer cells, rapid Mcl-1 upregulation in response to ABT-263 limits the extent to which apoptosis is induced in these cells." (PMID 31595181, 2019). "As treatment with MCL-1 targeting BH3-mimetic drugs induced apoptosis of breast cancer cells in vitro we tested the in vivo potential of such drugs." (PMID 29339815, 2018). "In these models targeting MCL-1 constrained the intrinsic apoptosis pathway and inhibited TN breast cancer growth." (PMID 29339815, 2018). "We have previously shown that anti-apoptotic Mcl-1 is related to paclitaxel resistance in prostate and breast cancer and that Mcl-1 over-expression is a frequent event in aggressive cancers." (PMID 30563080, 2018). "MDA-MB-468 cells were selected for further study as they expressed relatively high levels of MCL-1 and as a TN breast cancer cell line they are representative of a disease subtype that is in need of new therapies." (PMID 29339815, 2018). "We delivered siRNA sequences directed against Mcl-1 to LTED-selected ERα+ breast cancer cells as an experimental approach at targeted and highly selective Mcl-1 inhibition." (PMID 29343814, 2018). "We are investigating the therapeutic potential of targeting MCL-1 in breast cancer and the role of MCL-1 in breast cancer stem cells." (PMID 30405205, 2018). "In contrast to our findings with MCL-1, BCL-2 has been shown to be a favourable prognostic marker in breast cancer, often associated with slowly proliferating low grade ER-positive tumours." (PMID 29339815, 2018). "Our studies provide a rationale for testing MCL-1 inhibitors such as obatoclax in patients with HER2-positive breast cancer following progression on lapatinib treatment." (PMID 30305055, 2018). "This work significantly enhances our knowledge about the prognostic value of MCL-1 protein in breast cancer." (PMID 29339815, 2018).
breast carcinoma (continued). "MCL1 (myeloid cell leukemia-1), a member of the anti-apoptotic pro-survival Bcl-2 family, can be amplified in all subtypes of breast cancer." (PMID 30062102, 2018). "Distinct from other pro-survival Bcl-2 family members, the short half-life of MCL-1 protein led us to investigate MCL-1 protein expression in a breast cancer tissue microarray and correlate this with clinical data." (PMID 29339815, 2018). "For example, in LAML, it is appreciated that BCL-2 expression levels predict sensitivity to BCL-2 inhibition, and recent studies in breast cancer imply that BCL-XL function is critical for sensitivity to MCL-1 inhibition." (PMID 30158527, 2018). "Analysis of publicly available genomic and gene expression data demonstrates that MCL1 expression is frequently elevated in breast cancer." (PMID 29339815, 2018). "In agreement with this, we detected MCL-1 in cell lines representing the main subtypes of breast cancer." (PMID 29339815, 2018). "The prevalence of elevated MCL-1 in breast cancer and potential for therapeutic intervention shown here and by others suggests a functional role in early tumour development." (PMID 29339815, 2018). "The BH3 mimetic obatoclax (GX15–070), which inhibits MCL-1, has shown activity in pre-clinical models of both colon and breast cancer including SKBR3 and BT474 cell lines." (PMID 30305055, 2018). "The expression of the antiapoptotic protein MCL1 correlates with high tumor grade and lower survival rate in breast cancer." (PMID 29568373, 2018). "We next measured caspase-3/7 activity in ERα+ breast cancer cells 48 h after treatment with MCL1 si-NPs." (PMID 29343814, 2018). "Intriguingly, low levels of MCL-1 protein were correlated with poor prognosis in a cohort of Luminal A breast cancer patients." (PMID 29339815, 2018). "To understand the functional relevance of the cross-talk between pro- and anti-apoptotic proteins, we performed long-term viability assay in breast cancer cells depleted for both BOK/Mcl-1." (PMID 29156771, 2017). "To substantiate this notion, we tested the expression of other pro- and anti-apoptotic members of Bcl-2 family in BOK/Mcl-1 silenced breast cancer cells." (PMID 29156771, 2017). "The anti-apoptotic Bcl-2 family protein myeloid cell leukemia-1 (Mcl-1) plays an important role in breast cancer cell survival and chemoresistance." (PMID 28301598, 2017). "Since GSK3β is a substrate for Akt, which phosphorylates and inhibits it, we investigated if S6K2 regulates Mcl-1 degradation in breast cancer cells." (PMID 28301598, 2017). "For example, breast cancer cell lines and tumors of the growth phenotype had higher levels of the anti-apoptotic protein MCL-1 and lower levels of the critical pro-apoptotic protein BIM." (PMID 28446242, 2017). "We chose to use MDA-MB-231 and MDA-MB-468 cells for determining miR-296-5p function as well as regulation of BOK and Mcl-1 as these cell lines have lower levels of miR-296-5p and higher levels of BOK and Mcl-1 compared to other breast cancer cell lines." (PMID 29156771, 2017). "We examined the effect of NCTD on the expression of a panel of critical apoptosis-related proteins, including c-FLIP, XIAP, c-IAP-1, Survivin, Mcl-1, Bcl-xl and Bad, in these breast cancer cell lines." (PMID 28460471, 2017). "Knockdown of TDRD3 expression in breast cancer cells decreases the level of MCL-1, a known USP9X substrate, and sensitizes breast cancer cells to chemotherapy drug-induced apoptosis." (PMID 28101374, 2017). "The lower level of Mcl-1 in breast cancer specimens was unexpected given that Mcl-1 expression was previously shown to correlate with the tumor grade in breast cancer patients." (PMID 29156771, 2017).
breast carcinoma (continued). "In accordance with that, higher Mcl-1 expression was correlated with lower overall survival and relapse-free survival of breast cancer patients as revealed by the Kaplan-Meir analysis." (PMID 29156771, 2017). "Meta-analysis of TCGA data set revealed that like BOK, the levels of both miR-296 and Mcl-1 were significantly lower in breast cancer tissues compared to normal adjacent controls." (PMID 29156771, 2017). "Our date demonstrated that enforced miR-519d expression enhanced the cisplatin-induced apoptosis through the MCL-1 dependent mitochondria pathway in breast cancer stem cells." (PMID 28423543, 2017). "In contrast, several studies have indicated that MCL1 overexpression was a protective factor against breast cancer and can reduce tumor cell proliferation and arrest cell cycle progression." (PMID 27001083, 2016). "Here, we have modeled MCL-1 antagonism in breast cancer cell lines by inducible expression of a modified form (L62A/F69A double mutant) of the short isoform of BIM (BIMs2A/2A), which mimics the actions of a highly specific small molecule antagonist." (PMID 27931239, 2016). "In a preliminary gene expression analysis, we found that MCL-1 transcription was significantly up-regulated by aspirin in breast cancer cell line MDA-MB-231." (PMID 26918349, 2016). "Ionizing radiation-inducible microRNA miR-193a-3p induces apoptosis by directly targeting Mcl-1; miR-193b regulates Mcl-1 in Melanoma; miR-193b Modulates Resistance to Doxorubicin in Human Breast Cancer Cells by Downregulating MCL-1." (PMID 32309578, 2016). "In our study, cytoplasmic MCL-1 protein was detected in all clinico-pathological subtypes of invasive breast cancer and breast cancer cell lines." (PMID 27931239, 2016). "The MCL-1 gene is one of the most frequent focal amplifications in breast cancer, occurring in approximately 30% of cases." (PMID 27931239, 2016). "MiR-26a has been reported as tumor suppressor miRNA and inhibited proliferation and migration through repression of MCL-1 (an anti-apoptotic member of the Bcl-2 family) in breast cancer." (PMID 27232942, 2016). "Nonetheless, few insights have been available regarding the mechanisms responsible for MCL-1 overexpression in breast cancer." (PMID 27217294, 2016). "Overexpression of MCL-1 in breast cancers correlates with high tumor grade and a decrease in patient survival." (PMID 27217294, 2016). "In breast cancer tissues, loss of FBXW7 correlated with adverse prognosis markers and loss of FBXW7 and MCL1 or PLK1 accumulation were associated with diminished disease-free survival in paclitaxel-treated patients." (PMID 27409838, 2016). "While there have been several studies on the effects of CDK9i on breast cancer cells, relatively few relevant targets, other than MCL-1, have been widely reported." (PMID 26812885, 2016). "Consistent with the results obtained with glioma cells, silencing of Sirt3 expression facilitated the down-regulation of Mcl-1 and survivin protein, and promoted the induction of apoptosis in human breast cancer cells under hypoxia." (PMID 27270321, 2016). "Diagnostic biopsies of breast cancer patients were analyzed by immunohistochemistry for the expression of FBXW7, MCL1 and PLK1." (PMID 27409838, 2016). "Apoptosis was induced in breast cancer cells by 17-DR as confirmed by the down-regulation of Mcl-1 and Bcl-2, and up-regulation of Bax protein levels." (PMID 27658586, 2016). "The importance of targeting Mcl-1 in breast cancers is further supported by extensive studies conducted on anti-apoptotic Bcl-2 family proteins in other cancers." (PMID 25784482, 2015). "In summary, Bay 61–3606 downregulates Mcl-1 expression in breast cancer cells and sensitizes cancer cells to TRAIL-mediated apoptosis." (PMID 26720004, 2015). "This review will focus on the role of Bcl-2 family members in breast development, tumorigenesis and therapeutic resistance, and will highlight one member, Mcl-1, as a promising therapeutic target in breast cancers." (PMID 25784482, 2015).
breast carcinoma (continued). "There are only a few established links between the KLFs, anti-apoptotic BCL2 family proteins and HER2.52, 53, 54 In this study, we observed coexpression of KLF4/5 and MCL1 in human breast tumors and breast cancer models." (PMID 25789974, 2015). "Mcl-1 remains understudied in breast cancers as compared to other Bcl-2 family anti-apoptotic proteins." (PMID 25784482, 2015). "Currently, little is known regarding the contribution of Mcl-1 to breast cancer formation and therapeutic response." (PMID 25784482, 2015). "Specifically in the context of breast cancer, Mcl-1 has genetic or mRNA upregulation in 16/58 (28%) of human breast cancer cell lines as curated by the CCLE, while Bcl-2 is only aberrantly upregulated in 2/58 cases (3%)." (PMID 25784482, 2015). "We conclude that the miR-193b modulates resistance to doxorubicin in human breast cancer cells by downregulating MCL-1." (PMID 26526790, 2015). "A recent study on radiation and BH3 mimetics in breast cancer showed treatment with ABT-737 alone elevated Mcl-1." (PMID 26223311, 2015). "Fluorescence in situ hybridization (FISH) of the MCL1 region identified lung and breast cancers as having significantly higher frequencies of focal amplification, suggesting that these tumors depend on MCL-1 for survival." (PMID 26134786, 2015). "It has also been demonstrated that several miRNAs induce apoptosis by targeting MCL1 in acute myeloid leukemia, lung cancer, breast cancer, and ovarian cancer." (PMID 26504803, 2015). "Taken together, MCL-1 is a potential target through which miR-193b modulates doxorubicin resistance in human breast cancer." (PMID 26526790, 2015). "Recent efforts in developing an Mcl-1 specific inhibitor have been reported, although their efficacy in breast cancers and pre-clinical testing remains on the horizon." (PMID 25784482, 2015). "ABT-737 together with radiation, however, demonstrated a synergistic effect on breast cancer cells by downregulation of Mcl-1." (PMID 26223311, 2015). "Some of the derivatives were also active in intact human breast cancer cells where they reduced the levels of Mcl-1, induced programd cell death (apoptosis) and inhibited cell proliferation." (PMID 25076060, 2014). "Collectively, both the in vitro and in vivo results suggested that WNT5B-initiated MCL1 signaling dominantly controlled the overall outcome of breast cancer patients, especially in TNBC." (PMID 24564888, 2014). "The increased copy number of MCL1 was found in more than 10% of cancers, but the amplification was higher in lung and breast cancers." (PMID 24564888, 2014). "Estrogen seems to regulate Mcl-1 expression at both the protein and mRNA level in ERα+ breast cancer cell lines, suggesting that ER mediates this expression." (PMID 24971890, 2014). "This suggests that in ERα+ breast cancer cells, estrogen signaling is involved in up-regulating Mcl-1 transcription." (PMID 24971890, 2014). "High Mcl-1 levels contribute to chemo-resistance and radio-resistance, contribute to disease relapse and correlate with poor prognosis in breast cancer and other cancers." (PMID 25606592, 2014). "Some cancers, including primary breast cancer, demonstrate an association between USP9X and Mcl-1, a pro-survival BCL2 family member that is essential for stem and progenitor cell survival." (PMID 25606592, 2014). "To determine the role of ER, we evaluated the effect of estrogen on Mcl-1 expression in two ERα- breast cancer cell lines, SK-BR-3 and MDA-MB-231 cells." (PMID 24971890, 2014). "Mcl-1 is an important mediator of paclitaxel resistance in breast cancer and other tumors and a critical prosurvival protein." (PMID 24357640, 2014). "To explore the significance of aberrant expression of p-ERK1/2 in TNBC for cancer targeted gene therapy of BikDD, we investigated the correlation between p-ERK1/2 expression and expression of Bik, Bcl-2, Bcl-Xl and Mcl-1 in 114 breast cancer patient samples." (PMID 24637719, 2014).